MTA2 (metastasis associated 1 family member 2)
Diseases named in the same sentence as MTA2 in open-access papers (continued):
Sharing a sentence is not in itself a finding about the gene and the disease.
breast carcinoma (continued). "Increased expression of MTA2 leads to estrogen independent growth of human mammary carcinoma cells and increased expression of NFKB1 expression increases the invasive potential of carcinoma cells." (PMID 22060274, 2011). "Because of the role of MTA2 in breast cancer metastasis, we hypothesized it's the same reason for MTA1-induced metastasis inhibition." (PMID 30642362, 2019). "In estrogen receptor-alpha–negative breast cancer, MTA2 expression is associated with poor prognosis and enhanced metastasis in vitro and in vivo through Rho pathway activation." (PMID 31771219, 2019). "In this study, we aimed to examine the different roles that MTA1 and MTA2 may play in breast cancer metastasis and investigate their relationship." (PMID 30642362, 2019). "Furthermore, it has also been reported that MTA2 can alter the activity of Rho GTPase by regulating Rho GDIα in MDA-MB-231 breast cancer cells." (PMID 30642362, 2019). "Elucidating the difference between MTA1 and MTA2 may lead to an improved understanding of breast cancer metastasis." (PMID 30642362, 2019). "A high expression of MTA2 also contributes to lamellipodia formation in breast cancer cells." (PMID 31777601, 2019). "Binding with ERα, MTA2 could repress its transcriptional activity in breast cancer cells." (PMID 25929737, 2015). "Based on the findings of our study and previous research, MTA2 and HDAC2 show promise as potential targets for breast cancer treatment." (PMID 37483962, 2023). "AIB1 directly interacts and colocalizes with MTA2 to repress E-cadherin expression thereby promoting EMT, migration and pro-metastatic phenotype of estrogen deprived breast cancer cells." (PMID 33420368, 2021). "MTA1 and MTA2 have both been reported to be pivotal for epithelial-mesenchymal transition (EMT) and metastasis of breast cancer, while MTA3 has been reported to inhibit EMT." (PMID 30642362, 2019). "Both being potent breast cancer metastasis-promoting factors of the MTA family, the difference and relationship between MTA1 and MTA2 remain an enigma because of insufficient investigations." (PMID 30642362, 2019). "For example, the expression of ΔNp63 was suppressed by TRPS1-CHD4/NuRD(MTA2), which decommissioned TP63 enhancer leading to reduced metastatic ability of breast cancer cells and better survival of breast cancer patients." (PMID 30563971, 2018). "MTAP loss is associated with ER-, HER2- and TNBC status, features a distinctive GL with potential to impact both targeted and immunotherapies and enables emerging clinical trials testing MTA2 and PRMT5 inhibitors for patients with clinically advanced breast cancer." (PMID 36913304, 2023). "Although the specific mechanism and pathway interactions through which PIMREG promotes breast cancer remain unknown, our study identified correlations between PIMREG and MTA2, and HDAC2." (PMID 37483962, 2023). "Targeting MTA2 with a short hairpin RNA could reduce cell proliferation and inhibit metastasis by downregulating MMP-2 or MMP-9 expression in breast cancer and glioma cells." (PMID 31771219, 2019). "Both MTA1 and MTA2 have been reported to promote EMT and breast cancer metastasis." (PMID 30642362, 2019). "Scoring of the IHC staining of MTA1 and MTA2 indicated a negative correlation between the protein level of MTA1 and MTA2 in luminal B breast cancer tissues (P < 0.05), and representative images are shown." (PMID 30642362, 2019). "We investigated the roles of MTA1 and MTA2 in the metastasis of the ZR-75-30 luminal B breast cancer cell line, and we found that the overexpression of MTA1 inhibits the metastasis of ZR-75-30 cells by downregulating MTA2, which has not been clarified previously." (PMID 30642362, 2019).
pancreatic cancer (17 papers, 2012 to 2025). "For example, lncRNA MTA2TR upregulated the transcription of metastasis-associated protein 2 (MTA2) by recruiting activating transcription factor 3 to the MTA2 promoter region in pancreatic cancer." (PMID 40004471, 2025). "MTA2′s association with HIF-1α was previously shown in pancreatic cancer, as MTA2 deacetylases HIF-1α and consequently increases HIF-1α stability." (PMID 32640630, 2020). "Metastasis-associated protein 2 (MTA2) stabilizes the HIF-1α protein via deacetylation in pancreatic cancer, and its transcriptional regulator RNA MTA2TR is transcriptionally regulated by HIF-1α under hypoxic conditions." (PMID 32550915, 2020). "DIM also induced the expression of miR-146a, which resulted in reduced pancreatic cancer cell invasion via inhibition of metastasis-associated protein 2 (MTA-2), interleukin-1 receptor-associated kinase 1 (IRAK-1), and NFκB." (PMID 25853141, 2015). "In this work, we established AS1411-functionalized liposomes encapsulating MTA2 siRNA for selective delivery to pancreatic cancer cells." (PMID 40943389, 2025). "Consistently, our analysis using the database of cBioPortal for Cancer Genomics showed that MTA2 gene was amplified in several types of human cancer, including pancreatic cancer." (PMID 30814496, 2019). "In the present study, we found that Snail also recruited MTA2 to suppress the expression of PTEN in the human pancreatic cancer cells." (PMID 30814496, 2019). "In the present study, we demonstrated that MTA2 acted as a transcriptional repressor of PTEN in the human pancreatic cancer cells." (PMID 30814496, 2019). "Treatment of pancreatic cancer cells with isoflavone compounds (including 70.54% genistein), increased miR-146a expression, causing downregulation of EGFR, MTA-2, IRAK-1, and NF-κB, resulted in inhibition of cell invasion." (PMID 22928040, 2012). "The MTA2 expression level is closely related to the prognosis of tumors, and it has been reported that higher MTA2 expression is related to an adverse prognosis in pancreatic cancer patients." (PMID 37371463, 2023). "HIF-1α could inhibit E-cadherin expression via recruiting metastasis-associated protein 2 (MTA2)/HDAC1 complex to bind to E-cadherin promoter, inducing EMT in pancreatic cancer cells." (PMID 32587480, 2020). "We noticed that MTA2 was significantly upregulated in human pancreatic cancer tissues compared with that in non-cancer normal tissues, and a higher expression level of MTA2 was associated with a shorter overall survival time." (PMID 30814496, 2019). "Interestingly, PTEN was significantly downregulated in human pancreatic cancer tissues compared with that in normal tissues in the online public database, which displayed an opposite tendency with MTA2." (PMID 30814496, 2019). "Notably, a strong association between increased MTA2 mRNA expression and decreased PTEN mRNA expression was noticed in the human pancreatic cancer tissues from the online public PDAC databases." (PMID 30814496, 2019). "Meanwhile, in pancreatic cancer, HIF-1α-induced lncRNA-MTA2TR (MTA2 transcriptional regulator RNA) transcriptionally up-regulates the expression of oncogenic MTA2 (metastasis associated protein 2) by recruiting ATF3 (activating transcription factor 3) to the promoter area of MTA2." (PMID 32370770, 2020). "Overexpression of miR-146a inhibits the proliferation and survival of breast, prostate, and pancreatic cancer cells through the downregulation of its targets including ROCK1, EGFR, and MTA-2." (PMID 28435518, 2017). "Notably, MTA2 overexpression or PTEN knockdown confers resistance to the growth-suppressive effects of 10 μmol/L BITC but not 20 μmol/L BITC in the pancreatic cancer cells." (PMID 30814496, 2019).
hepatocellular carcinoma (12 papers, 2019 to 2024). A malignant tumor that arises from hepatocytes. "Metastasis Associated 1 Family Member 2 (MTA2) acts as a transcriptional repressor by binding to the promoter region of Willin/FRMD6 in hepatocellular carcinoma." (PMID 34831245, 2021). "Studies have shown the overexpression of metastasis-associated protein 2 (MTA2) to be associated with hepatocellular carcinoma (HCC) progression." (PMID 31777601, 2019). "Our previously published results show that MTA2 serves as a prognostic factor for human cervical cancer, renal cancer, and hepatocellular carcinoma; however, less is known about the clinical significance of MTA2 in human osteosarcoma patients." (PMID 39248711, 2024). "Metastasis-associated protein 2 (MTA2) was upregulated in hepatocellular carcinoma (HCC) cells and induced the accumulation of βHB, increased the level of H3K9bhb, and exerted a cascading effect on HCC cell stemness and progression." (PMID 35428309, 2022). "MTA2 overexpression has been reported in various human cancers, including gastrointestinal, lung, renal, breast and hepatocellular carcinoma." (PMID 36454786, 2022). "Upregulation of MTA2 was revealed in many cancers, such as cervical cancer, hepatocellular carcinoma, pancreatic ductal adenocarcinoma, contributing an increasingly aggressive phenotype 33." (PMID 31410216, 2019). "We constructed a nomogram in TCGA-LIHC, performed single-cell sequencing (scRNA-seq) analysis of MTA2 in hepatocellular carcinoma (HCC), and screened drugs for the treatment of HCC." (PMID 37371463, 2023). "Our previous study also revealed that MTA2 is overexpressed in hepatocellular carcinoma (HCC), and MTA2 knockdown reduces the mestastasis of HCC cell lines by inhibiting MMP2 expression." (PMID 33958583, 2021). "Knockdown of MTA1 or MTA2 had the same effect as knockdown of SMYD3 on proliferation and invasion of hepatocellular carcinoma cells." (PMID 36575438, 2022). "Given that the mRNA expression of BDH1 could be transcriptionally regulated by MTA2-triggered R-loop in hepatocellular carcinoma stem cells, we hypothesized that HG- and PA-induced BDH1 reduction might be mediated by MTA2." (PMID 38015723, 2023).
cervical cancer (10 papers, 2013 to 2024). A primary or metastatic malignant neoplasm involving the cervix. "Here, we showed that MTA2 is highly expressed in cervical tumor tissues and is associated with the poor prognosis of cervical cancer." (PMID 33958583, 2021). "Ectopic expression of MTA2 enhances the metastatic potential of cervical cancer cells via promoting AP1-mediated MMP12 expression." (PMID 38474064, 2024). "We further explored the in vivo effects of MTA2-knockdown on the metastasis of cervical cancer cells by using a xenograft model." (PMID 33958583, 2021). "To explore the role of MTA2 in the metastatic potential of cervical cancer cells, we established MTA2-knockdown cervical cancer cells to investigate the effects of MTA2 knockdown on cell motility, invasiveness, and in vivo metastasis." (PMID 33958583, 2021). "We explored the role of YB1 in the suppressed migration and invasion of cervical cancer cells in response to MTA2 knockdown." (PMID 33958583, 2021). "In the present study, we further demonstrated that silencing MTA2 clearly inhibits the metastasis of cervical cancer cells by inducing the ASK1/MEK3/p38/YB-1 axis and the consequent suppression of MMP12." (PMID 33958583, 2021). "According to these results, AP-1 plays an important role in MTA2-mediated MMP12 expression in cervical cancer cells." (PMID 33958583, 2021). "We also showed that MTA2 is highly expressed in cervical tumors, suggesting that MTA2/MMP12 could be a potential poor prognostic marker for cervical cancer." (PMID 33958583, 2021). "However, the role of MTA2 in the metastatic ability of cervical cancer cells remains poorly understood." (PMID 33958583, 2021). "Collectively, these findings indicated that MTA2 plays a key role in regulating MMP12 expression in HPV-positive cervical cancer cells, suggesting that MTA2 may be involved in the HPV-induced carcinogenesis of cervical cancer." (PMID 33958583, 2021). "MTA2 was first identified in quickly dividing cells in cervical cancer." (PMID 25929737, 2015). "Sp1 knockdown increased kallikrein-10 (KLK10) expression, indicating that the miR-7/Sp1 axis acts as a key regulator of MTA2, affecting both KLK10 expression and mobility in cervical cancer cells." (PMID 38632598, 2024). "Previous studies have found that MTA2 regulates MMP12 expression and is involved in cervical cancer metastasis." (PMID 36741260, 2023). "MTA2 and MMP12 were highly expressed in cervical cancer HeLa and SiHa cells but weakly expressed in CC7T/VGH and C33A cells." (PMID 33958583, 2021). "Results showed that MTA2 and MMP12 were highly expressed in cervical cancer cells, and MTA2 knockdown reduced MMP12 expression and inhibited the metastasis of cervical cancer cells in xenograft mice." (PMID 33958583, 2021). "Thus, we first investigated whether MTA2 regulates MMP12 in human cervical cancer cell lines." (PMID 33958583, 2021). "Collectively, targeting both MTA2 and MMP12 may be a promising strategy for the treatment of cervical cancer." (PMID 33958583, 2021). "Moreover, we demonstrated that MTA2 knockdown can downregulate MMP12 expression and the metastatic potential of HPV-positive cervical cancer cells." (PMID 33958583, 2021). "Here, we observed that ASK1 activation is crucial to the downregulation of MMP12 through the MEK3/p38 cascade in response to MTA2 knockdown, suggesting that the inhibited ASK1/MEK3/p38 axis may play an important role in the progression of cervical cancer." (PMID 33958583, 2021). "Moreover, ASK1 silencing not only restored the metastatic potential of MTA2-knockdown cervical cancer cells and MMP12 expression but also diminished the activation of MEK3 and p38 in response to MTA2 knockdown." (PMID 33958583, 2021). "Thus, we hypothesized that MTA2 may regulate MMP12 expression and is involved in cervical cancer metastasis." (PMID 33958583, 2021).
glioma (10 papers, 2015 to 2025). A benign or malignant brain and spinal cord tumor that arises from glial cells (astrocytes, oligodendrocytes, ependymal cells). "Moreover, knockdown of MTA2 in human glioma cells could modulate the expression of the AKT-regulated downstream genes, such as p21 and p5341, suggesting a possible interaction between MTA2 and the PI3K/AKT signaling pathway." (PMID 30814496, 2019). "HDAC-related genes upregulated in IDH1/2mut glioma include HDAC2/4/5, KDM1A, CHD4, MTA2/3, SIRT1/2, PHF21A, and BRMS1L." (PMID 34424450, 2021). "For example, in glioma, miR-526b-5p and miR-548b-3p acted as tumor suppressors by targeting WEE1 and MTA2, respectively." (PMID 33221765, 2020).
pancreatic ductal adenocarcinoma (6 papers, 2019 to 2025). An infiltrating adenocarcinoma that arises from the epithelial cells of the pancreas. "For instance, MTA2 promotes carcinogenesis and progression of pancreatic ductal adenocarcinoma by inhibiting the expression of PTEN." (PMID 38474064, 2024). "MTA2 was observed to be highly expressed in pancreatic ductal adenocarcinoma (PDAC) and correlated with aggressive properties and poor prognosis." (PMID 31777601, 2019).
lung carcinoma (5 papers, 2010 to 2025). "Not only is important in lung cancer initiation but metastasis, as NF-κB induce the expression of metastasis-associated protein 2 (MTA2) in the lung." (PMID 41008623, 2025). "(2020) found that MTA2 negatively regulates NF-κB through forming the MTA2/NuRD corepressor complex and interacting with RelA to inhibit lung cancer growth and inflammation." (PMID 41159000, 2025). "MTA2 may act as a new symbol and target in the treatment of lung cancer." (PMID 20704817, 2010). "The results show that the occurrence and development of lung cancer may be related with MTA2." (PMID 20704817, 2010). "Furthermore, this study suggests that epigenetic regulators, including the NuRD (MTA2) and ncBAF (BRD9) complexes, contribute to EGFR and GLI-1 expression and interact with MEOX2 in lung cancer cells." (PMID 39971779, 2025).
non-small cell lung carcinoma (5 papers, 2010 to 2020). A group of at least three distinct histological types of lung cancer, including non-small cell squamous cell carcinoma, adenocarcinoma, and large cell carcinoma. "MTA2 overexpression has been correlated with advanced TNM stages, tumor size, and lymph-node metastasis in non-small-cell lung cancer." (PMID 23825676, 2013). "In non-small cell lung cancer, ki-67 index in MTA2 positive tissues was higher than that in negative ones." (PMID 25929737, 2015).
colon cancer (3 papers, 2016 to 2022). "Indeed, to date, HBD-3 has only been shown to inhibit tumour cell migration by suppressing vascular endothelial growth factor in head and neck cancer cells or down-regulating MTA2 (metastasis-associated 1 family, member 2) expression of colon cancer cells." (PMID 26657293, 2016). "When SIRT1-Flag tagged expression plasmid was transfected into Human colon cancer HCT116 cell line, the acetylation levels of SMARCA5, MTA2, HMGA1, EGFR, CHD4 and GOT2 decreased as equal amounts of the proteins were immunoprecipitated." (PMID 28676654, 2017).
lymph node metastasis (3 papers, 2010 to 2019). "There was some expression of MTA2 in partial NSCLC and it was correlated with differentiation degree, clinical stage and lymph node metastasis." (PMID 20704817, 2010). "The expression of MTA2 had negative correlation with differentiation degree of NSCLC but had positive correlation with clinical stage and lymph node metastasis (P < 0.05), moreover, it had no obvious correlation with age, gender and pathological type (P > 0.05)." (PMID 20704817, 2010).
breast tumor (2 papers, 2019 to 2020). "As the TCGA data shows, the mRNA level of the MTA family, containing MTA1, MTA2 and MTA3, is higher in breast tumor tissues than in normal tissues (p=1e-12 in MTA1, p=9.7e-9 in MTA2, p<2.22e-16 in MTA3)." (PMID 33282725, 2020). "Downregulation of MTA2 through the suppression of both the PI3K/AKT and MAPK/ERK pathways ultimately leads to the inhibition of breast tumor growth." (PMID 31777601, 2019).
esophageal cancer (2 papers, 2021 to 2022). A primary or metastatic malignant neoplasm involving the esophagus. "TCGA database was used to analyze the relationship between expression of MTA2, MT1E and MT1X in esophageal cancer and prognosis and survival, and the analysis results showed that low expression of MT2A, MT1E and MT1X was associated with poorer overall survival." (PMID 36466860, 2022).
esophageal squamous cell carcinoma (2 papers, 2019 to 2024). Esophageal squamous cell carcinoma (ESCC) is a type of esophageal carcinoma (EC) that can affect any part of the esophagus, but is usually located in the upper or middle third. "Overexpression of MTA2 contributes to the growth, metastasis, and epithelial-mesenchymal transition (EMT) progression of esophageal squamous cell carcinoma through the EIF4E-Twist pathway." (PMID 39248711, 2024).
nasopharyngeal carcinoma (2 papers, 2019 to 2024). A carcinoma arising from the nasopharyngeal epithelium. "Other reports have demonstrated that MTA2 overexpression could activate AKT and upregulate MMP-7 expression in nasopharyngeal carcinoma cells." (PMID 31771219, 2019).
oral squamous cell carcinoma (2 papers, 2022 to 2023). "In oral cancer, HOTAIR mediates the suppression of cell proliferation and promotion of apoptosis and promotes the invasion and metastasis of oral squamous cell carcinoma through metastasis-associated gene 2 (MTA2)." (PMID 36924407, 2023).